IL17A (interleukin 17A)
Diseases named in the same sentence as IL17A in open-access papers (continued):
Sharing a sentence is not in itself a finding about the gene and the disease.
airway hyperresponsiveness (63 papers, 2008 to 2026). "We demonstrate that camel milk suppresses airway hyperresponsiveness, Th2 and Th17 cell recruitment, and associated cytokines (IL-4, IL-5, IL-13, IL-17A), while reducing dendritic cell activity and CCL17 expression in the lungs." (PMID 40577410, 2025). "Interleukin 17A (IL-17A) produced by Th17 cells can stimulate neutrophil airway inflammation and is associated with increased airway hyperresponsiveness." (PMID 36743692, 2023). "Neonatal S. pneumoniae infection exacerbated adulthood hallmark features of AAD, with enhanced airway hyperresponsiveness and increased neutrophil recruitment into the airways, increased Th17 cells and interleukin (IL)-17A productions." (PMID 25816135, 2015). "Surprisingly, adoptive transfer of syngeneic HDM-pulsed bone marrow derived mDCs (BMDCs) to the lungs of C3H mice markedly enhanced lung IL-17A production, and rendered them susceptible to allergen-driven airway hyperresponsiveness." (PMID 19060952, 2008). "At the molecular level, the HDM challenge elevated the expression of major Th2 cytokines (IL-4 and IL-13), IL-17a, and muc5ac, which are key mediators of airway hyperresponsiveness and mucus overproduction." (PMID 39682780, 2024). "When microcapsules containing live S. cerevisiae UFMG A-905 were added, the bread also diminished airway hyperresponsiveness and increased the concentrations of IL17A." (PMID 38655128, 2024). "When adding microcapsules, the bread also diminished airway hyperresponsiveness and increased IL17A concentrations." (PMID 38655128, 2024). "Upon chronic ozone exposure, IL-17A also induces inflammation, neutrophil recruitment, and airway hyperresponsiveness." (PMID 32161582, 2020). "During acute ozone exposure, IL-17A is produced by γδ T cells and iNKT and induces neutrophil recruitment and airway hyperresponsiveness." (PMID 32161582, 2020). "Elevated levels of IL-17A displayed in sputum of asthmatics were correlated not only with neutrophilia, but also with an airway hyperresponsiveness provoked with methacholine." (PMID 31779093, 2019). "In addition, it has been reported that SLPI inhibits airway hyperresponsiveness through IL-17A regulation." (PMID 38673881, 2024). "IL- 33 was found to cooperate with IL-17A to exacerbate airway hyperresponsiveness in mice." (PMID 26214807, 2015). "Depletion of IL-17A by i.p. injection of a neutralizing monoclonal antibody reduced neutrophil recruitment into the airways, alleviated airway inflammation and decreased airway hyperresponsiveness." (PMID 25816135, 2015). "We hypothesised that IL-17A may play an important role in airway hyperresponsiveness, pulmonary inflammation and emphysema induced by chronic exposure to ozone." (PMID 23505509, 2013). "Interestingly, our study showed that rPTX3 treatment exacerbated inflammatory cell infiltration, airway hyperresponsiveness, mucus hypersecretion, airway remodeling and production of inflammatory cytokine, especially IL-17A, in both eosinophilic and neutrophilic asthma models." (PMID 32938460, 2020). "With the addition of microcapsules, the bread effects were more pronounced, with a significant reduction in airway hyperresponsiveness, percentage of eosinophils, and Th2 cytokines concentrations (IL5 and IL13), and an increase in the IL17A concentrations." (PMID 38655128, 2024). "Our mouse model indicated that IL-17A contributed to the airway hyperresponsiveness during late stage of RSV infection, while NPAs were collected at a single point in time, the failure to detect a difference may be due to the kinetics of IL-17A increases." (PMID 36793128, 2023). "Ablation of T cell–derived IL-10 increased the IFN-γ and IL-17A response to HDM, reducing IL-13 levels and airway eosinophilia without affecting IgE levels or airway hyperresponsiveness." (PMID 31445933, 2020).
endometriosis (62 papers, 2013 to 2026). The growth of functional endometrial tissue in anatomic sites outside the uterine body. "Compared to healthy controls, IL-17A concentrations were significantly increased in patients with endometriosis and decreased in plasma after excision of the lesion, reinforcing the association of IL-17A with the pathophysiological process of endometriosis." (PMID 36762287, 2023). "It was documented that increases in the level of IL-17A and the presence of Th17 in peritoneal fluid correlate positively with the severity of endometriosis and infertility associated with this disorder." (PMID 35935991, 2022). "Additionally, the researchers suggest that IL-17A plays a role in recruiting macrophages, and M2 macrophages have indeed been demonstrated to facilitate extracellular matrix remodeling and neovascularization, closely linked to the development of endometriosis." (PMID 39456936, 2024). "Recent studies have shown increased expression of IL-17A in ectopic endometriosis lesions, which stimulates the production of angiogenic and pro-inflammatory factors, thereby promoting the maintenance of endometriotic lesions." (PMID 41488658, 2025). "Higher levels of serum IL-37 and IL-10, and significantly lower levels of serum IL-17A and IL-2 were detected in patients with endometriosis." (PMID 39595927, 2024). "Cytokines such as IL-37, IL-17A, IL-10, and IL-2 play essential roles in modulating immune responses in endometriosis." (PMID 39595927, 2024). "Studies have demonstrated that Th17 cells and IL-17A have essential functions in the onset of endometriosis." (PMID 39355310, 2024). "There are increased levels of pro-inflammatory cytokines, such as TNF-α, IL-1β, IL-6, and IL-17A, in the PF and ectopic lesions of patients with endometriosis, promoting the inflammation and development of endometriosis." (PMID 36865552, 2023). "Our findings further confirmed that IL-17A gene expression increased in eutopic and ectopic endometriosis tissue as compared to control groups." (PMID 38868448, 2023). "IL-4 was found to stimulate the proliferation of ESCs, while IL-17A was shown to enhance the migration of neutrophils in endometriosis." (PMID 37834449, 2023). "Immunohistochemistry revealed the localization of IL-17A+ cells were observed in the tissues taken from endometriosis." (PMID 35457278, 2022). "It is reported that IL-17A is chemotactic for macrophages via its receptor, IL-17RA, and can also induce M2 polarization in lung cancer 127, which is also demonstrated in endometriosis." (PMID 35582411, 2022). "And IL-27 was considered to induce the IL-10 and IL-17A double-producing Th17 cells in endometriosis." (PMID 35582411, 2022). "IL-17A enhanced angiogenesis and the production of inflammatory cytokines and chemokines, possibly enhancing inflammatory reaction in endometriosis." (PMID 35457278, 2022). "Interleukin-17A (IL-17A) can induce M2 macrophage polarization in other disease models and IL-17A is elevated in the plasma and endometriotic lesions of women with endometriosis." (PMID 32117261, 2020). "In this study, using both in vitro and in vivo approaches, we demonstrate previously unreported roles of IL-17A in macrophage recruitment and polarization in the context of endometriosis." (PMID 32117261, 2020). "This study provides a basis for future investigations to examine the response of macrophage populations to the elevated systemic levels of IL-17A in women with endometriosis." (PMID 32117261, 2020). "Further, in a syngeneic mouse model of endometriosis, IL-17A treatment increased macrophages in the peritoneum, which were also M2 in phenotype." (PMID 32117261, 2020). "To further understand both the direct and indirect role of IL-17A in the recruitment and polarization of peritoneal macrophages into an M2 phenotype, we used our well-established mouse model of endometriosis." (PMID 32117261, 2020).
endometriosis (continued). "Because macrophages play an important role in the progression of endometriosis, we wanted to assess the effect of IL-17A on monocytes and macrophages." (PMID 32117261, 2020). "Mechanistically, IL-17A was thought to contribute to the establishment and maintenance of endometriosis lesions by promoting angiogenesis and pro-inflammatory environment in the peritoneal cavity." (PMID 33013364, 2020). "These IL-10 and IL-17A double-producing Th17 cells promote the growth, adhesion, invasion and deep infiltration of ESCs, thus accelerating the progression of endometriosis." (PMID 28300844, 2017). "Furthermore, other studies have shown heightened levels of IL-17A in both the PF and plasma of endometriotic patients compared to controls, along with the production of IL-17A by lesions of endometriosis." (PMID 39456936, 2024). "In addition, studies have demonstrated in vivo and in vitro that IL-17A can induce M2 macrophage in endometriosis." (PMID 38430256, 2024). "IL-17A promotes M2 polarization to facilitate endometriosis progression." (PMID 38430256, 2024). "IL-17A may play a role in the development of endometriosis by stimulating inflammatory responses, angiogenesis, and proliferation of endometriotic stromal cells." (PMID 35935991, 2022). "Additionally, in their study, immunohistochemistry revealed the localization of IL-17A-positive cells in the stroma and surrounding the vasculature in matched eutopic endometrium and ectopic lesion samples from women with endometriosis." (PMID 35582411, 2022). "Although studies have shown the potential role of IL-17A in the direct polarization of macrophages into M2 phenotype, it was unknown whether IL-17A plays a similar role in endometriosis." (PMID 32117261, 2020). "Therefore, IL-17A could be the stimuli that mediates macrophage recruitment and M2 polarization in endometriosis." (PMID 32117261, 2020). "There are other components of innate immunity, including TNF-α, IL-1β, IL-6, IL-17A, ICAM-1/LFA-1, and HMGB-1, that participate in the pathogenesis of endometriosis." (PMID 36865552, 2023). "The expression of IL-2, IL-17A, and EGF was higher in the non-endometriosis group than in the eutopic endometrium group." (PMID 35269619, 2022). "Interestingly, increases in IL-17A, IL18, TNFSF13B, and TNF signaling have all been previously identified in endometriosis conditions." (PMID 35682747, 2022). "Gross evaluation of endometriosis lesions did not reveal any major macroscopic anomalies for size and appearance of lesions in mice treated with either IL-17A or PBS." (PMID 32117261, 2020). "IL-17A triggered the expression of angiogenic factors, pro-inflammatory cytokines, and chemotactic cytokines, including granulocyte colony-stimulating factor (G-CSF), CXCL12, CXCL1, and CX3CL1, which play a crucial role in promoting the establishment and growth of endometriosis lesions." (PMID 36865552, 2023). "And IL-17A produced by neutrophils stimulates endometrioma stromal cells to secrete growth-regulated oncogene-α (GRO-α), a member of the C-X-C family of chemokines, thereby recruiting more neutrophils and inducing the formation and maintenance of endometriosis." (PMID 36762287, 2023). "However, PBS-Treated Mice also showed decreased plasma levels of Eotaxin, IL-9, IL-13, and MIP-1α, suggesting that the difference may stem from the induction endometriosis, and not from the IL-17A injection." (PMID 32117261, 2020).
acne (60 papers, 2014 to 2026). An inflammatory process of the sebaceous glands which is characterized by comedones, nodules, papules and/or pustules on the skin. "In our study, both Zn deficiency and C. acnes induced a decrease in skin IL-17A levels, potentially a key factor in acne vulgaris exacerbation due to Zn deficiency." (PMID 40507073, 2025). "Research indicates that the IL17/Th17 pathway is activated in acne lesions, with IL-17A being highly expressed in the epidermis and lymphocytes of patients with acne vulgaris." (PMID 40507073, 2025). "These cells are induced to release IFN-γ and IL-17A, fostering a combined Th17 and Th1/Th17 host response that contributes to the inflammatory landscape of acne." (PMID 38791344, 2024). "T lymphocytes have been demonstrated to appear first in early acne lesions and IL-17-producing cells with increased IL-17A tissue expression have also been found in lesions." (PMID 35966699, 2022). "Activated memory/effector CD4+ T cells induced IL-17A production by human mast cells, implying a contribution of mast cells to development of acne vulgaris." (PMID 35874756, 2022). "Activation of the Th17 cell that induced IL-6 secrete IL-17A and IL-17F which main effector cytokines in acne lesions." (PMID 32380665, 2020). "In the current study we examined the inflammatory reaction and especially the IL-23/Th17/IL-17A axis in lesions of acne in vivo." (PMID 25153527, 2014). "The Zn-de-Model group exhibited higher levels of these cytokines than the Model group, with increases of 51.74% for TNF-α, 11.91% for IL-1β, 118.06% for IL-17A, 19.64% for MMP9, and 17.05% for CXCL1/KC, indicating that Zn deficiency leads to more severe skin inflammation in acne-like mice." (PMID 40507073, 2025). "IL-17A-producing mast cells were detected in the perifollicular area of acne vulgaris lesions." (PMID 35874756, 2022). "Furthermore, significantly higher numbers of IL-17A positive (IL-17A+) cells were detected by immunohistochemistry both in the papillary dermis and around sebaceous follicles in acne lesions of Finnish patients." (PMID 25153527, 2014). "In conclusion, we demonstrated the presence of IL-17A+ cells, which were mainly lymphocytes, in clinically early visible inflamed acne lesions, and also the activation of cytokines, chemokines and antimicrobial peptides known to be typical for the Th17/IL-17 pathway." (PMID 25153527, 2014). "Our results in two independent groups of acne patients show that the cytokines involved in the differentiation of Th17 cells and the expression of the main effector cytokines IL-17A and IL-17F were significantly expressed in lesions of acne at mRNA and protein level." (PMID 25153527, 2014). "Indeed, the presence of IL-17A-positive T cells and Th17-related cytokines in acne lesions suggests that the Th17 pathway is activated and may be crucial to the disease process." (PMID 39744637, 2024). "In summary our results demonstrate the presence of IL-17A positive T cells and the activation of Th17-related cytokines in acne lesions, indicating that the Th17 pathway is activated and may play a pivotal role in the disease process, possibly offering new targets of therapy." (PMID 25153527, 2014). "The presence of IL-17A-positive T cells and Th17-related cytokines (IL-1β, IL-6, TGF-β, IL23p19) is also characteristic of acne lesions." (PMID 39744637, 2024). "A clinical trial on anti-IL-17A therapy for moderate to severe acne found no significant reduction in inflammatory lesions compared to a placebo." (PMID 41465543, 2025). "Anti-IL-17A therapy has not been found to be significantly effective in inflammatory lesions in patients with moderate to severe acne." (PMID 38666916, 2024). "Importantly, immunohistochemistry revealed significantly increased numbers of IL-17A positive T cells and CD83 dendritic cells in the acne lesions." (PMID 25153527, 2014).
acne (continued). "We defined the markers of T cell subsets at mRNA level and studied Th1 (T-bet), Th17 (IL-17A), Treg (Foxp3) cells, cytotoxic CD8+ T-cells and CD68 macrophages and CD83 positive activated dendritic cells in clinically early acne lesions by immunohistochemistry both phenotypically and proportionally." (PMID 25153527, 2014). "The expression of cytokines IL-6, IL-12p40, INF-γ and TGF-β have not been studied earlier in acne lesions as also noticed by Thiboutot and co-workers, nor cytokines IL-17A, IL-17F, IL-23p19, IL-22 and chemokines CCL20 and CSF2." (PMID 25153527, 2014). "Furthermore, Th17 cell products IL-17A, IL-22, IL-26, TNF and IL-17 induced chemokines CSF2 and CCL20 were also expressed at higher levels in acne lesions." (PMID 25153527, 2014).
Salmonella Infections (60 papers, 2012 to 2025). Infections with bacteria of the genus SALMONELLA. "Previous studies have reported on the role of CD4-TCR1- cells as additional IL-17A-producers during Salmonella infection." (PMID 40438105, 2025). "CD8αα+hiCD4-TCR1- cells in chickens not only produce IL-17A but also respond more rapidly than γδ T cells during Salmonella infection." (PMID 40438105, 2025). "At 9 dpi, IL-17A and IL-22 transcription in response to Salmonella infection were significantly elevated in TCR Cγ−/− compared to wild-type chickens." (PMID 40438105, 2025). "Although a few studies addressed the involvement of γδ T cells, it has been suggested that they contribute to host defense in Salmonella infection in mice, where they have been described as IL-17A-producers in spleen and intestinal mucosa." (PMID 34451970, 2021). "IL-17A-deficient mice demonstrate a modest increase in bacterial dissemination following oral Salmonella infection, suggesting a protective role for IL-17 in the maintenance of the mucosal barrier at early infection time points." (PMID 32722409, 2020). "Following Salmonella infection, the Th17 response in the CD4+ T cell population shifts to a Th1-biased response, and IL-17A, which is increased by Salmonella infection, stimulates intestinal epithelial cells to enhance the production of antimicrobial proteins and chemokines." (PMID 34484221, 2021). "The increased abundance of IL-17A-IL-22+ cells CD4+ T cells after Salmonella infection of eSPF+SFB compared to eSPF mice triggered the question of whether these SFB-induced cells are also detectable in steady state conditions." (PMID 34566952, 2021). "Systemic and typhoidal mouse models of Salmonella infection indicate that IL-23's function is largely masked by IL-12 and that IL-23 enhances protection against systemic Salmonella infection primarily through IL-22 and to a lesser extent IL-17A." (PMID 22624013, 2012). "As reported by others, we found that TRMs in conjunction with the activation of IL-17A, IFN-γ and IL-12p70 secreting cells are collectively needed for protection against Salmonella infection in mice." (PMID 37457702, 2023). "Strikingly, mice from this eSPF barrier almost completely lost their ability to induce innate IL-17A and IL-22 producing CD4+ T cells upon Salmonella infection and cytokine production ability was successfully restored upon colonization with SFB." (PMID 34566952, 2021). "Taken together, these data demonstrate that presence of SFB alone is sufficient for the rapid production of IL-17A and IL-22 by CD4+ T cells after Salmonella infection." (PMID 34566952, 2021). "FACS analysis of cecal CD4+ T cells after Salmonella infection of eSPF+SFB mice revealed that ~70% of IFN-γ producing CD4 T cells did not secrete IL-17A or IL-22 indicating a classical Th1 phenotype." (PMID 34566952, 2021). "Besides, they identifiy that SFB induces, in the context of the eSPF microbiota, the acquisition of diverse cytokine-production profiles in CD4+ T cells, including a subset that produces IL-22 but not IL17A after Salmonella infection." (PMID 34566952, 2021). "We characterized the activation and memory state of SFB-induced IL-17A and/or IL-22 producing CD4+ T cells based on the expression of specific markers including CCR6, CD44, and CD62L in the presence or absence of Salmonella infection." (PMID 34566952, 2021).